NDRG1 (N-myc downstream regulated 1)
Diseases named in the same sentence as NDRG1 in open-access papers (continued):
Sharing a sentence is not in itself a finding about the gene and the disease.
neuropathy (6 papers, 2013 to 2022). A disorder affecting the nervous system that manifests with pain, tingling, numbness, and/or muscle weakness. "The N-myc downstream-regulated gene (NDRG1) is implicated in neuropathies with comparable symptoms or clinical signs both in humans and in Greyhound dogs." (PMID 23393557, 2013). "Despite the ubiquitous expression of NDRG1 in the epithelium of different tissues, the pathologic changes reported from humans, rodents, and dogs with NDRG1-associated neuropathies are restricted to the peripheral nervous system, and, to a lesser degree, the central nervous system." (PMID 31029158, 2019). "In CMT4D, NDRG1 has been shown to cause degradation of myelin leading to severe neuropathy." (PMID 27716814, 2016). "Low NDRG1 expression in nerve tissue present within samples of surgical resection may identify subjects at risk for severe paclitaxel-induced neuropathy." (PMID 27716814, 2016). "Our findings suggest NDRG1 may be a potential novel biomarker for CIPN, with low NDRG1 expression in nerve tissue identifying patients at greater risk for paclitaxel-induced neuropathy for whom an alternative drug/regimen may be considered." (PMID 27716814, 2016). "A detailed mapping of the cellular and subcellular distribution of NDRG1, as well as post-translational modifications of the protein in peripheral nerves of dogs, is one prerequisite for deciphering NDRG1’s roles in neuropathies." (PMID 31029158, 2019). "Elucidating the normal subcellular localization and post-translational modifications of NDRG1 in diverse tissues holds one key to understanding its roles in both neuropathies and malignancies." (PMID 31029158, 2019). "We therefore proceeded to study NDRG1 expression level in human nerve tissues to assess its relationship with paclitaxel induced neuropathy." (PMID 27716814, 2016). "13/54 (24%) subjects with an NDRG1 score < = 7 developed severe neuropathy, compared to only 4/57 (7%) in those with a score >7 (p = 0.017)." (PMID 27716814, 2016). "We investigated the relationship between the Charcot-Marie-Tooth protein NDRG1 and paclitaxel-induced neuropathy." (PMID 27716814, 2016). "We compared the level of NDRG1 expression in nerve tissue in patients who did or did not develop severe paclitaxel-induced neuropathy, and found patients with severe paclitaxel-induced neuropathy to have lower NDRG1 IHC scores in human nerve tissue." (PMID 27716814, 2016). "ROC analysis performed to determine the predictive validity of NDRG1 for severe neuropathy revealed an AUC of 0.74 (p = 0.0013), with a score of 7 yielding the highest sensitivity (77%) with the least loss of specificity (56%)." (PMID 27716814, 2016). "Although the predominant pathologic findings in dogs with NDRG1-associated neuropathies were reported to be axonal, no NDRG1 signal was detected in the axons." (PMID 31029158, 2019). "It is therefore possible that the abnormal curvature of the spine in Ndrg1 KO mice may be rather more attributable to the neuropathy than the primary disorder of osteoclasts." (PMID 26778110, 2016). "We previously performed a single nucleotide polymorphism (SNP) study to analyze the association of several genetic variants with CIPN in an Asian population, and found an N-myc downstream regulated gene (NDRG)-1 SNP, rs2233335, to correlate with paclitaxel-induced neuropathy." (PMID 27716814, 2016). "However, it could also be an unspecific result of the nerve pathology, so further studies are needed to elucidate the role of phosphorylated NDRG1 in the pathogenesis of neuropathies." (PMID 31029158, 2019). "The mean nerve NDRG1 expression score was 5.4 in patients with severe neuropathy versus 7.7 in those without severe neuropathy (p = 0.0019)." (PMID 27716814, 2016).
polyneuropathy (6 papers, 2010 to 2023). A disease or disorder affecting more than one nerve. "Polyneuropathy in the juvenile Greyhound was associated with a 10 bp deletion in exon 15 of the canine NDRG1 gene." (PMID 38003185, 2023). "In both humans and dogs, specific mutations affecting NDRG1 cause progressive polyneuropathies, classified as CMT4D in the former." (PMID 31029158, 2019). "We propose that disease-causing mutations in NDRG1 can disrupt signaling in myelinating Schwann cells, causing disturbance in myelin homeostasis and axonal-glial cross talk, thereby precipitating polyneuropathy." (PMID 31029158, 2019). "Our study concluded that historical and recent phenotypic polyneuropathy cases were carrying the same NDRG1-mutation." (PMID 28464941, 2017). "Since NDRG1 is mutated in Greyhounds with a similar polyneuropathy, this gene was considered a candidate gene for AMPN." (PMID 23393557, 2013). "An inherited polyneuropathy in which the causative mutation is a 10 bp deletion in exon 15 of NDRG1 has recently been identified in Greyhound dogs." (PMID 23393557, 2013). "DNA sequencing revealed a 10 bp deletion in the NDRG1 gene, which is perfectly associated with the polyneuropathy phenotype in Greyhound show dogs." (PMID 20582309, 2010). "In conclusion, by positional cloning we have identified the 10 bp deletion in the canine NDRG1 gene as the most likely causative mutation for polyneuropathy in Greyhound show dogs." (PMID 20582309, 2010). "A 10 bp deletion in canine NDRG1 exon 15 (c.1080_1089delTCGCCTGGAC) was perfectly associated with the polyneuropathy phenotype of Greyhound show dogs." (PMID 20582309, 2010). "Our finding of a NDRG1 mutation in dogs with polyneuropathy provides a valuable model for human medicine possibly useful for the investigation of the pathogenesis and therapeutic trials." (PMID 20582309, 2010). "Additionally, early-onset progressive polyneuropathy in Alaskan Malamutes was linked to a non-synonymous variant (G>T) occurring in exon 4 of the of the same (NDRG1) gene." (PMID 38003185, 2023). "Association of the NDRG1 mutation with the polyneuropathy phenotype." (PMID 20582309, 2010). "The naturally occurring polyneuropathy dog model may represent a better model for human CMT4D than Ndrg1-deficient mice because of the dog's body size and structure and the resulting similarity to the human situation." (PMID 20582309, 2010). "Moreover, the fact that NDRG1 is also mutated in Greyhounds and humans with some forms of polyneuropathy supports the hypothesis that the G>T substitution causes AMPN." (PMID 23393557, 2013). "A homozygous mutation has been identified in the N-myc downstream-regulated gene 1 (NDRG1) in recent cases of polyneuropathy in Alaskan malamute dogs from the Nordic countries and USA." (PMID 28464941, 2017). "RT-PCR on peripheral nerve cDNA confirmed that the NDRG1 mRNA is normally spliced in Greyhounds with polyneuropathy." (PMID 20582309, 2010). "As the age of onset, the clinical course of the disease, and the described nerve pathology in polyneuropathy affected Greyhound show dogs is highly similar to CMT4D affected children and Ndrg1-deficient mice, we analyzed the canine NDRG1 for possible mutations." (PMID 20582309, 2010). "Taken together, we think that the most likely explanation for the polyneuropathy phenotype in affected Greyhound show dogs is lack of NDRG1 caused by the 10 bp deletion." (PMID 20582309, 2010). "We thus have identified a candidate causative mutation for polyneuropathy in Greyhounds and identified the first genetically characterized canine CMT model which offers an opportunity to gain further insights into the pathobiology and therapy of human NDRG1 associated CMT disease." (PMID 20582309, 2010). "Forty-one historical dogs were included in the pedigree only (they were not NDRG1 tested) and of those, clinical information allowing a diagnosis of polyneuropathy was available for nine dogs." (PMID 28464941, 2017).
lung adenocarcinoma (5 papers, 2013 to 2025). A carcinoma that arises from the lung and is characterized by the presence of malignant glandular epithelial cells. "NDRG1 was first identified as calcium-associated protein 43 (Cap43), a gene upregulated in A549, human lung adenocarcinoma epithelial cells, in a dose- and time-dependent manner in response to non-toxic levels of nickel compounds using differential display technique." (PMID 40378957, 2025). "Clinical sample analysis from lung adenocarcinoma patients further emphasized the importance of NDRG1 as a therapeutic target." (PMID 40539245, 2025). "NDRG1 drives lactate accumulation and histone lactylation in lung adenocarcinoma, promoting immunosuppression via M2 macrophage polarization and CD8+ T cell inhibition." (PMID 40539245, 2025). "As for the role played by PTK7, it has been shown that PTK7 could enhance cancer cell adhesion by stabilizing NDRG1, and the PTK7-NDRG1 axis is recognized as a key factor in the development of resistance to AZD9291 (osimertinib) in lung adenocarcinoma cells." (PMID 39474113, 2024).
prostate tumors (5 papers, 2017 to 2023). "NDRG1 is phosphorylated by PIM1 at serine 330 (pS330), and the level of NDRG1 pS330 is associated higher grade prostate tumors." (PMID 33398037, 2021). "In this study, we demonstrate that NDRG1‐deficient prostate tumors have decreased integrin expression and reduced cell adhesion and motility." (PMID 28371345, 2017). "Altogether, these data suggest that loss of NDRG1 in prostate tumor cells may impart them with the ability to survive anoikis, consequently increasing the metastatic outcome." (PMID 28371345, 2017). "In particular, NDRG1 expression in prostate tumors with lymph node or bone metastasis is significantly reduced as compared with those with localized prostate cancer." (PMID 28371345, 2017). "Considering this information, we examined the protein levels of NDRG1 pS330, total NDRG1, and PIM1 by immunohistochemistry using tissue microarrays containing primary prostate tumors and adjacent non-cancer tissue." (PMID 33398037, 2021).
viral infection (5 papers, 2017 to 2022). "Recently, some groups have reported that NDRG1 might be associated with viral infection." (PMID 30811506, 2019). "It additionally involves apoptosis, glycolytic, and lipid metabolism in cancer cells, and virus infection process was also related to NDRG1." (PMID 33790969, 2021). "Overall, our study demonstrates a previously unreported relationship between PRRSV, NDRG1, and lipophagy in the context of viral infection." (PMID 31189711, 2019). "The significance of our research is that we demonstrate a previously unreported relationship between PRRSV, NDRG1, and lipophagy in the context of viral infection." (PMID 31189711, 2019). "It is thus intriguing to hypothesize that NDRG1 expression may act as an intermediate molecular phenotype linking NDRG1 genotype with observed reproductive variation, and that this relationship may be further affected by viral infection." (PMID 35953767, 2022).
and sensory neuropathy (4 papers, 2008 to 2021). "It is known that NDRG1 is involved in lipid metabolism and the myelination of neurons, as the expression of truncated isoforms of NDRG1 through mutations has been associated with demyelinating diseases, such as hereditary motor and sensory neuropathy-Lom." (PMID 34572031, 2021). "The NDRG1 gene is located within this interval and NDRG1 mutations have been shown to cause hereditary motor and sensory neuropathy-Lom in humans (CMT4D)." (PMID 20582309, 2010). "N-myc downstream regulated gene 1 (NDRG1) is a responsible gene for a hereditary motor and sensory neuropathy-Lom (Charcot–Marie–Tooth disease type 4D)." (PMID 26778110, 2016). "NDRG1 was identified as a gene responsible for hereditary motor and sensory neuropathy-Lom, which is an early-onset peripheral neuropathy that progresses to severe disability in adulthood." (PMID 18334952, 2008).
demyelinating disorders (4 papers, 2014 to 2022). "NDRG1 encodes a cytoplasmic signaling protein that plays a role in development and maintenance of myelin, and mutations in this gene cause demyelinating disorders." (PMID 31456662, 2019). "Only a few studies have attempted to obtain molecular insights into the functions of NDRG1 in CNS demyelinating disorders." (PMID 36499320, 2022). "In humans, Alaskan Malamute and Greyhound, germline NDRG1 mutations cause the demyelinating disorder CMT4D and Ndrg1 deficient mice show defects connected to myelin sheath maintenance." (PMID 24498060, 2014).
inflammatory breast carcinoma (4 papers, 2020 to 2024). An advanced, invasive breast adenocarcinoma characterized by the presence of distinct changes in the overlying skin. "Additionally, inflammatory breast cancer patients with high NDRG1 expression exhibit reduced overall survival vs. patients with low NDRG1 expression; likewise, more aggressive disease was observed in NDRG1-high mouse models of inflammatory breast cancer." (PMID 36765657, 2023).
meningioma (4 papers, 2015 to 2021). A generally slow growing tumor attached to the dura mater. "Another interesting finding in our study is that NDRG1 hypermethylation in meningiomas with regrowth was associated with unfavorable regrowth-free survival." (PMID 34385566, 2021). "We further show elevated expression of SGK1 accompanied by constitutive activation of SGK1 as detected by phosphorylation of its specific target NDRG1, in human arachnoidal and meningioma cells with NF2 loss." (PMID 26219339, 2015). "Increased expression of NDRG1 is associated with poor patient outcomes which might be the case for meningiomas as well." (PMID 32974197, 2020). "Here we establish that, in addition to mTORC1 activation, mTORC2-dependent activation of SGK1/NDRG1 is commonly seen in human meningioma cells, which remains unaffected by rapamycin treatment." (PMID 26219339, 2015). "Our results convincingly show that activation of the mTORC2-target SGK1/NDRG1 in human meningioma cells is sensitive to AZD2014, but insensitive to rapamycin." (PMID 26219339, 2015). "For this purpose, 44 WHO grade I meningiomas, including 8 showing regrowth after radiosurgery, were analysed for Ki-67 and NDRG4 protein expression, loss of 1p36 and promotor hypermethylation of the genes NDRG1-4, SFRP1, HOXA9 and MGMT." (PMID 34385566, 2021). "As per the heatmap it is visible that NDRG1, MRC2, and COPS8 is highly abundant in the higher grades of meningiomas whereas more abundances of COL14A, COL12A1 were found in the non-tumor controls." (PMID 32974197, 2020). "MSP for NDRG1-4, SFRP1, HOXA9 and MGMT was performed on 41 meningioma samples and 10 nontumoral control brain tissue samples." (PMID 34385566, 2021).
metastatic cancer (4 papers, 2015 to 2024). A carcinoma which has spread from the original site of growth to another anatomic site. "In cancer, the NDRG1 gene is considered to engage in the suppression of metastasis to negatively associate with the migration of metastatic cancer cells." (PMID 35448004, 2022). "As NDRG1 overexpression forms cleaved caspase 3 products, triggering apoptosis in metastatic cancer cells, we examined if high NDRG1 expression could cause cell death." (PMID 39444004, 2024). "Second, in two independent datasets, NDRG1 expression is significantly higher in BrMs than in primary BCs, both in a paired analysis of 45 primary‐metastatic cancer pairs (p = 0.0347; paired Student t test) and in an unpaired analysis of 90 samples (p = 0.0497; Mann–Whitney U test)." (PMID 40530439, 2024). "The invasion inhibitory action of VPA in metastatic cells is, thus, apparently mediated through the metastasis suppressor NDRG1, and the restoration of metastasis suppressors by the action of the epigenetic modulator VPA could be a promising strategy for metastatic cancer treatment." (PMID 26692161, 2015).
non-small cell lung carcinoma (4 papers, 2018 to 2025). A group of at least three distinct histological types of lung cancer, including non-small cell squamous cell carcinoma, adenocarcinoma, and large cell carcinoma. "In non-small cell lung cancer, elevated levels of p-NDRG1 (Thr346) were associated with decreased overall survival." (PMID 40332138, 2025).
preeclampsia (4 papers, 2012 to 2021). Preeclampsia is a hypertensive disorder of pregnancy that is characterized by new-onset hypertension with proteinuria presenting after 20 weeks of gestation, and depending on mild or severe forms may initially present with severe headache, visual disturbances, and hyperreflexia. "We also observed high DMC density regions in genes for which placental DNAm and/or expression differences have been associated with preeclampsia, including INHBA, JUNB, TEAD3, NDRG1, and CGA." (PMID 33407091, 2021). "Moreover, only one article was found describing an increased expression of NDRG1 during preeclampsia." (PMID 22873350, 2012). "FLT1, LEP, INHA and ENG genes were identified according to the literature, however, we also found other genes as FLNB, INHBA, NDRG1 and LYN highly significant but underexplored during normal pregnancy or preeclampsia." (PMID 24219996, 2013).
sarcoma (4 papers, 2022 to 2024). A usually aggressive malignant neoplasm of the soft tissue or bone. "Additionally, NDRG1 can interact with the DNA polymerase clamp in Kaposi’s sarcoma-associated herpesvirus infected cells." (PMID 36213122, 2022). "The sarcoma and LUAD signatures had three common genes (PPFIA4, BNIP3L, NDRG1)." (PMID 35079065, 2022).
Autoimmunity (3 papers, 2015 to 2022). The occurrence of an immune reaction against the organism's own cells or tissues. "Nonetheless, Ndrg1-knockout T cells could clearly enhance inducible autoimmunity, suggesting a role of Ndrg1 in dampening down autoimmunity." (PMID 26507712, 2015). "In the absence of Ndrg1, effector/memory T cells eventually become hyperresponsive, which can aggravate autoimmunity initiated by other stimuli." (PMID 26507712, 2015). "However, while NDRG1 deficiency is a well-described cause of CMT in humans, autoimmunity or immunodeficiency are not described in CMT4d33,74–76." (PMID 36357486, 2022).
colorectal tumors (3 papers, 2005 to 2024). "In human colorectal tumors, miRNA‐483‐3p expression inversely correlated with NDRG1 and directly correlated with EMT transcription factor expression and poor prognosis." (PMID 36862005, 2023). "In Caco-2 cells, the differentiation-related gene NDRG1, which is expressed during differentiation and down-regulated in colorectal neoplasms, was up-regulated at 12 hrs." (PMID 16001974, 2005).
gastric tumor (3 papers, 2016 to 2023). "Conversely, DDIT4, NDRG1, and CHAC1 showed lower levels in stomach tumor tissues than that in normal tissues." (PMID 32457731, 2020).
inflammatory bowel disease (3 papers, 2023 to 2024). A spectrum of small and large bowel inflammatory diseases of unknown etiology. "Some studies propose that NDRG1 may play a key role in the development of inflammatory bowel disease and may serve as specific therapeutic targets for the treatment of inflammatory bowel disease." (PMID 36445533, 2023). "Evidence has shown that Ndrg1 may play important roles in the progression of inflammatory bowel disease and may be used as a promising therapeutic candidate for the control of intestinal inflammation." (PMID 37370489, 2023).